GSTP1 (glutathione S-transferase pi 1)
Diseases named in the same sentence as GSTP1 in open-access papers (continued):
Sharing a sentence is not in itself a finding about the gene and the disease.
breast carcinoma (continued). "GSTP1 exosomal mRNA from breast cancer cells resistant to Adriamycin, for instance, confer resistance to previously sensitive cells." (PMID 29515996, 2018). "The results were controversial in breast cancer, a number of studies found overexpressed GSTP1 gene, while others reported underexpressed GSTP1 gene." (PMID 30043549, 2018). "Then lv-GSTP1 and GSTP1-shRNA plasmids were constructed to investigate the potential of GSTP1 in regulating chemoresistance of breast cancer." (PMID 29116019, 2017). "In the current study, we investigated the effects of CLDN6 expression in response to various anti-cancer drugs in breast cancer, and explore the role of GSTP1 in CLDN6 mediated chemoresistance in human breast cancer cells." (PMID 29116019, 2017). "At the same time, we also verified elevated expression of GSTP1 in multidrug resistant breast cancer cells MCF-7/MDR as compared to MCF-7 cells." (PMID 29116019, 2017). "This is in support with the previous findings have suggested that, CDH1 and GSTP1 promoter regions tend to be methylated in breast cancer cells." (PMID 28979331, 2017). "GSTP1 overexpression have been reported in many cancers, such as breast cancer, colon cancer, kidney cancer, lung cancer, and ovarian cancer." (PMID 27367026, 2016). "In breast cancer, GSTP1 CpG island hypermethylation has been found to be significantly associated with tumor size, lymph node metastasis and relapse-free survival." (PMID 26393654, 2015). "To date, several studies have investigated the methylation patterns of the GSTP1 in breast cancer patients, yet the data are greatly variable due to differences among studies." (PMID 26585467, 2015). "Polymorphisms in GSTM1, GSTP1, and GSTO1 enzymes increase the risk of developing breast cancer and hepatocellular carcinoma." (PMID 26682223, 2015). "The current meta-analysis demonstrated that the methylation level of GSTP1 was significantly higher in breast cancer patients than that in normal controls, which indicated its potential role in the etiology of breast cancer." (PMID 26585467, 2015). "Our results showed that breast cancer exhibited significantly higher frequency of GSTP1 methylation than normal controls (OR = 7.85, 95 % CI = 5.12–12.01)." (PMID 26585467, 2015). "For all genes except GSTP1, statistically significant differences were found between the methylation status in tumor and tumor-distant tissues of breast cancer patients." (PMID 26370119, 2015). "Aberrant methylation of the GSTP1 often occurs in different cancer types including those of liver, prostate, and breast cancer." (PMID 26585467, 2015). "Jhaveri and Morrow initially published that methylation status of GSTP1 promoter contributes significantly to the levels of GSTP1 expressed in ER-negative and ER+-positive breast cancer cell lines." (PMID 25076909, 2014). "Lycopene treatment has been shown to have a potential role in demethylation, as it has been shown to partially demethylate the GSTP1 promoter and restore the GSTP1 expression in breast cancer cells." (PMID 25389438, 2014). "Previous studies have proved that GSTP1 was variably expressed in malignant tumor tissues with a low level in lymphoma and breast cancer, while over-expressed were found in lung cancer, head and neck tumors and colon cancer." (PMID 23437223, 2013). "The direct co-culture studies revealed the up-regulation of CDKN2A, a cell cycle regulator, and GSTP1, a gene responsible for the detoxification of drugs, which have been shown to be up-regulated in multi-drug resistant breast cancer." (PMID 24176089, 2013). "The results confirmed that the breast cancer cells with the GSTP1 105Val/Val genotype exhibited increased sensitivity to 4-HC, which is an active derivative of CTX in vivo, than the cells with the Ile/Ile genotype." (PMID 23826324, 2013).
breast carcinoma (continued). "To analyze the relationship between the GSTP1 Ile105Val genotype of breast cancer patients and their prognosis after CTX-based chemotherapy, we compared the 5-year DFS rate between patients with Val allele and those with Ile/Ile genotype." (PMID 23826324, 2013). "Among the members of the GST superfamily, GSTM1, GSTT1 and GSTP1 genotypes are considered to be the most related to the development of many cancers because their roles in lung cancer, acute leukemia and breast cancer have been identified in previous studies." (PMID 23717494, 2013). "RASSF1A, ABCB1 and GSTP1 showed significantly higher quantitative methylation levels in late stage compared to the early stage breast carcinoma." (PMID 24093668, 2013). "We further investigated the effect of the GSTP1 Ile105Val genotype on breast cancer drug resistance through in vitro cellular experiments." (PMID 23826324, 2013). "Our results further demonstrated that the GSTP1 105Val genotype provided a good prognosis for breast cancer patients in a Chinese population after receiving CTX-based chemotherapy (HR = 0.77, 95% CI: 0.45-0.91)." (PMID 23826324, 2013). "The genotypic frequencies of the GSTP1 Ile105Val SNP in women of North China: the breast cancer versus control groups." (PMID 23826324, 2013). "The genotypic distributions of GSTP1 Ile105Val were evaluated based on a large cohort of women with breast cancer and healthy populations in North China." (PMID 23826324, 2013). "In our study, GSTP1 was found to be hypermethylated in different stages of breast carcinomas, for early stages (I and II) our results are in agreement with previous reports." (PMID 24093668, 2013). "The GSTP1 105Val genotype is an unfavorable factor for healthy females, however, it is a favorable factor for the cytotoxic efficacy of chemotherapy for breast cancer patients." (PMID 23826324, 2013). "In this study, we examined the polymorphic frequency of GSTP1 Ile105Val genotype in 920 breast cancer patients and 783 healthy controls in women of North China." (PMID 23826324, 2013). "The comparison between control and breast cancer patient subjects revealed a significant difference among the three GSTP1 Ile105Val genotypes (Ile/Ile, Ile/Val and Val/Val)." (PMID 23826324, 2013). "The results provide further evidence that the GSTP1 Ile105Val genotype affects the therapeutic response and survival of breast cancer patients treated with CTX." (PMID 23826324, 2013). "In the two disease groups, GSTP1 methylation was a significant event (in early breast cancer cases; P= 0.05; in locally advanced breast cancer; P= 0.03)." (PMID 23226781, 2012). "We observed that GSTP1 promoter hypermethylation is present in one-third (34.4%) of human breast carcinomas, which was well within the previous reported frequency range (13 to 38.9%)." (PMID 23226781, 2012). "In female breast cancer, GSTP1 hypermethylation is correlated with high-grade ductal carcinoma in situ and high-grade invasive breast cancer, presence of lymph node metastasis and poor outcome." (PMID 22765268, 2012). "ESR1 and GSTP1 promoter hypermethylation seem to be involved in development and/or progression of high-grade male breast cancer." (PMID 22765268, 2012). "Methylated samples exhibited a loss of gene expression, suggesting that the silencing of the GSTP1 gene by CpG island DNA methylation plays an important role in the development of breast cancer." (PMID 23226781, 2012). "Studies have investigated the methylation status of GSTP1 in invasive breast cancer and a different study revealed GSTP1 promoter methylation to be an early event in breast cancer." (PMID 23226781, 2012). "MBD2 has been reported to mediate epigenetic silencing of 14-3-3σ in TRAMP C1 cells and human LNCaP prostate cells, and has been shown to be involved in the transcriptional repression of GSTP1 in MCF-7 breast cancer cells." (PMID 20062804, 2010).
breast carcinoma (continued). "Recently, we reported the haplotype structure to influence the level of DNA methylation of the GSTP1 promoter in breast cancers and to affect patient survival." (PMID 20338046, 2010). "We found little statistical evidence that PAHs interacted with GSTT1, GSTM1, GSTP1, and GSTA1 polymorphisms to further increase breast cancer risk." (PMID 19440493, 2009). "We estimated the breast cancer risk associated with multiple polymorphisms in the GST gene (GSTA1, GSTM1, GSTP1, and GSTT1) and the interaction with PAH–DNA adducts and cigarette smoking." (PMID 19440493, 2009). "Hypermethylation of CpG dinucleotides at the 5′ transcriptional regulatory region has been shown to be sufficient to inhibit GSTP1 transcription in the MCF-7 breast cancer cell line when mediated by the methyl-CpG-binding domain (MBD) protein MBD2." (PMID 16434992, 2006). "The main result emerging from this study is that GSTP1 expression can be taken into account in the management of breast cancer patients receiving adjuvant chemotherapy." (PMID 16434992, 2006). "This study was mainly designed to evaluate the clinical impact (DFS and OS) of MDR1, MRP1 and GSTP1 gene expression on the management of patients with breast cancer treated by adjuvant chemotherapy." (PMID 16434992, 2006). "GSTP1 expression can be considered to be an independent prognostic factor for DFS in patients receiving adjuvant chemotherapy for breast cancer." (PMID 16434992, 2006). "In conclusion, our findings suggest that a low level of GSTP1 gene expression is an independent predictive factor of poor 5-year DFS in patients treated by adjuvant chemotherapy for breast cancer." (PMID 16434992, 2006). "We studied the expression of multidrug resistance gene 1 (MDR1), multidrug resistance-associated protein (MRP1), and glutathione-S-transferase P1 (GSTP1) using a standardised, semiquantitative rt–PCR method performed on frozen samples of breast cancer tissue." (PMID 16434992, 2006). "MBD2 has also been reported to be involved in the repression of GSTP1 transcription in breast cancer cells." (PMID 16168120, 2005). "However, the presence of both GSTP1 and GSTO2 polymorphisms together was also found to be associated with an increased risk of breast cancer, particularly in premenopausal women." (PMID 40724836, 2025). "According to a Danish cohort study involving premenopausal women diagnosed with non-metastatic breast cancer, carriers of the GSTP1 rs1138272 and CYP3A rs10273424 genetic variants exhibited elevated mortality rates." (PMID 39598531, 2024). "Association of the PMR of GSTP1 and RARB genes and the risk of breast cancer." (PMID 37548362, 2023). "High expression of GSTP-1 in breast cancer has been reported to result in chemoresistance and thus high expression of GSTP1 in Black men with PCa may predict a poor response to chemotherapy." (PMID 36901912, 2023). "As a result, GSTP1 methylation is crucial for the study of breast cancer." (PMID 37901797, 2023). "For example, GSTP1 overexpression is a marker of cell proliferation in a variety of tumors, such as transitional cell carcinoma of the bladder, renal epithelial renal cell carcinoma, ovarian cancer, breast cancer, and colorectal cancer." (PMID 36688005, 2023). "This case–control study aimed to determine the association between the promoter methylation ratio (PMR) of RARB and GSTP1 genes (separately and as a group) with breast cancer and its clinical‐pathological variables in Peruvian patients, using a liquid biopsy approach." (PMID 37548362, 2023). "Additionally, GSTP1 expression was found to be higher in adriamycin‐resistant cells, and higher GSTP1 expression was also found in breast cancer tissues from subjects with progressive/stable disease versus those with partial/complete response." (PMID 35906899, 2023). "In early breast cancer events, GSTP1 hypermethylation also happens." (PMID 37901797, 2023).
breast carcinoma (continued). "Thus, many studies have shown that the expression and/or co-expression of several genes, such as ERCC1, RRM1, TOP1, TOP2α, TUBB3, TYMS, and GSTP1, in tumor tissues is closely related to chemoresistance and prognosis in breast cancer patients (BC)." (PMID 35204496, 2022). "GSTP1 is a tumor suppressor gene, hypermethylation of GSTP1 was significantly associated with patients having macroscopic sentinel LNM compared with those with microscopic or no sentinel node metastasis in breast cancer, which is consistent with our results." (PMID 36454866, 2022). "Other authors found that the presence of another disorder in the GSTP1 gene (in particular, methylation) in tumor tissue closely correlates with the clinical and pathological features of breast cancer, which indicates the possibility of using this gene for tumor diagnosis and prognosis." (PMID 35204496, 2022). "Lee and collaborators recruited 3035 cases matched with 3037 population controls sampling from the “Shanghai Breast Cancer Study” A GSTP1 haplotype (namely, the Val/Val genotype) significantly correlated with a higher risk of developing breast tumor (displaying an OR of 1.50 (95% CI 1.12–1.99))." (PMID 32085420, 2020). "Additionally, GSTP1 was recently shown to modulate glycolytic metabolism in breast cancer cells by enhancing glyceraldehyde-3-phosphate dehydrogenase (GAPDH) activity." (PMID 32526885, 2020). "Other authors found that EVs from adriamycin-resistant breast cancer cells contained high amounts of glutathione S-transferase P1 (GSTP1, a phase II metabolic enzyme capable of detoxifying damaging chemicals from cells), which was transferred to sensitive cells." (PMID 32384712, 2020). "The role of GSTP1 polymorphisms in solid tumor breast cancer is not well defined due to preliminary results deriving from two meta-analyses on a large number of women." (PMID 31357662, 2019). "Importantly, identification of GSTP1 in circulating exosomes from peripheral blood of patients was correlated with worst prognosis in breast cancer patients treated with Adriamycin." (PMID 29515996, 2018). "Finally, quantitation of the methylation levels in MDA-MB-453 cell line confirmed a hypermethylated phenotype at CDH1 and GSTP1 promoters beside a differential methylation pattern at DNMT3B promoter in breast cancer." (PMID 28979331, 2017). "Recent evidence indicated that GSTP1 directly involved in chemoresistance in multiple cancer cells, we believed that GSTP1 may be an important gene in regulating chemoresistance in breast cancer MCF-7 cells." (PMID 29116019, 2017). "However, quantitation of methylation confirmed a hypermethylated phenotype at CDH1 and GSTP1 promoters as well as a differential methylation pattern at DNMT3B promoter in breast cancer." (PMID 28979331, 2017). "Finally, immunohistochemistry was used to explore the relationship between CLDN6 and GSTP1 expression in breast cancer tissues." (PMID 29116019, 2017). "This substitution decreases the enzymatic activity of glutathione-S-transferase P1 (GSTP1) and alters the pharmacokinetics of cyclophosphamide, which may influence treatment outcomes and toxicity for breast cancer." (PMID 29069838, 2017).
breast carcinoma (continued). "In the current study, we explored the role of CLDN6 in breast cancer chemoresistance and the underlying mechanism, and found that high level expression of CLDN6 conferred chemoresistance on MCF-7 and MCF-7/MDR cells to ADM, 5-FU, and DDP through GSTP1." (PMID 29116019, 2017). "Immunohistochemistry was used to detect GSTP1 expression in breast cancer tissue from 175 patients." (PMID 28978147, 2017). "However, the role of GSTP1 promoter methylation in the occurrence of breast cancer and its relationship with tumor stage and histological grade has not been fully elucidated." (PMID 26585467, 2015). "Moreover, a high concordance between tumor and blood DNA methylation of GSTP1 was reported in studies conducted on paired tumor tissue and blood samples from breast cancer patients." (PMID 26585467, 2015). "This indicated that blood DNA methylation of GSTP1 could reflect alterations in the tumor and the ease of obtaining blood samples makes it a potential biomarker for diagnosis of breast cancer." (PMID 26585467, 2015). "Furthermore, our results revealed that GSTP1 promoter methylation was more often observed in late-stage breast cancer patients compared with early-stage ones (OR = 1.84, 95 % CI = 1.32–2.58)." (PMID 26585467, 2015). "Therefore, we conducted a meta-analysis of the published clinical studies to evaluate the effect of GSTP1 promoter methylation on breast cancer patients." (PMID 26585467, 2015). "Therefore, we aimed to investigate possible associations between germline genetic polymorphisms within GSTM1, GSTT1, GSTP1, SULT1A1 and UGT1A1 genes and breast cancer clinicopathological characteristics together with disease progression." (PMID 25648141, 2015). "Our study showed that the methylation level of GSTP1 increased significantly in late-stage compared to the early stage breast carcinomas, suggested that breast cancer patients with GSTP1 promoter hypermethylation may have a biologically aggressive phenotype." (PMID 26585467, 2015). "It has also been demonstrated that the hypermethylation of GSTP1 gene promoter frequently occurs in breast cancer and may result in inactivation of GSTP1 expression, thus lead to cancer progression." (PMID 26585467, 2015). "Interestingly, lycopene also reactivated GSTP1 gene expression through reduced promoter methylation in MDA-MB-468 breast cancer cells." (PMID 25076909, 2014). "However, the ability of lycopene to affect epigenetic changes has this far only been examined in one study in which lycopene was shown to demethylate the promoter of the GSTP1 in a breast cancer cell line." (PMID 25389438, 2014). "The results indicate that GSTP1 Ile105Val affects breast cancer cell response to CTX in vivo." (PMID 23826324, 2013). "To investigate the effects of the GSTP1 Ile105Val genotype on breast cancer drug resistance in vitro, we analyzed the mRNA expression levels, protein levels and the GSTP1 Ile105Val genotype in different breast cancer cell lines." (PMID 23826324, 2013). "Here we report that the variant Val allele of GSTP1 (rs1695) was associated with increased risk of all-cause mortality, but not breast cancer-specific mortality, in a cohort of 533 breast-cancer survivors." (PMID 24083102, 2013). "GSTP1, which is involved in the detoxification of carcinogenic polycyclic aromatic hydrocarbons, has been investigated extensively in relation to different types of cancer, such as breast cancer, bladder cancer, oesophageal cancer, and so on." (PMID 23977100, 2013). "A recent meta-analysis showed that GSTP1 105Val was associated with an increased breast cancer risk in Chinese populations but not in non-Chinese populations, which is consistent with our results." (PMID 23826324, 2013).